KANSL1 (KAT8 regulatory NSL complex subunit 1)
Diseases named in the same sentence as KANSL1 in open-access papers (continued):
Sharing a sentence is not in itself a finding about the gene and the disease.
KANSL1 also shares sentences with these, for which no sentence is quoted: autism (2 papers); breast carcinoma (2); chronic myelogenous leukemia (2); cognitive deficits (2); Dementia with Lewy Bodies (2); Parkinson’s (2); 3-methylglutaconic aciduria type 1 (1); acute myeloid leukemia (1); Angelman syndrome (1); Anxiety (1); atrial fibrillation (1); atrial septal defect (1); autism spectrum disorder (1); autosomal dominant inherited disorder (1); Bohring-Opitz syndrome (1); cardiofaciocutaneous syndrome (1); Coffin-Siris syndrome (1); cognitive decline (1); colorectal cancer (1); colorectal tumors (1); depression (1); developmental dysplasia of the hip (1); diabetes (1); frontotemporal dementia (1); heart diseases (1); heart failure (1); Hip dysplasia (1); Hypertension (1); intracranial hemorrhage (1); Kabuki syndrome (1).
A further 23 diseases each share a sentence with KANSL1 in 1 paper.